PNPLA3 (patatin like domain 3, 1-acylglycerol-3-phosphate O-acyltransferase )
Diseases named in the same sentence as PNPLA3 in open-access papers (continued):
Sharing a sentence is not in itself a finding about the gene and the disease.
steatosis (continued). "In fact, whereas I148 PNPLA3 homozygous patients showed very mild and often uncomplicated steatosis, heterozygous and homozygous M148 patients were strongly at risk of severe steatosis." (PMID 22927922, 2012). "Accordingly, stratifying CB2 polymorphism on I148M PNPLA3 variant, we have noticed that the effect of R63 CB2 variant on NASH appearance was emphasized in the sub-group of patients carrying the M148 PNPLA3, which is associated to severe steatosis." (PMID 22927922, 2012). "Overall, these data improve our understanding of the mechanism by which PNPLA3 I148M causes steatosis and could lead to novel therapies to treat MASLD." (PMID 39814233, 2025). "In addition to being the strongest determinant for the presence of MASLD compared to healthy controls, PNPLA3 rs738409[G] also conferred the highest risk of steatosis severity and modified the presence of portal fibrosis." (PMID 41311807, 2025). "Also, a common genetic variant (rs738409) coding for patatin-like phospholipase domain-containing 3 (PNPLA3) is associated with fat accumulation in the liver and increases the risk of steatosis, inflammation, fibrosis, and HCC." (PMID 40141037, 2025). "PNPLA3 is of therapeutic interest and a recent clinical trial demonstrates that targeting PNPLA3 in patient that is homozygous for the I148M variant with siRNA reduces steatosis." (PMID 39814233, 2025). "The main risk factors for post-LT MASLD identified in previous studies are diabetes, hypertension, hyperlipidemia, obesity/weight gain, genetic polymorphism PNPLA3, graft steatosis, LT indication (i.e., MASH, HCV, alcoholic liver disease) and immunosuppression." (PMID 41130087, 2025). "Therefore, the PNPLA3 (148M) variant is associated with the accumulation of PNPLA3, leading to steatosis." (PMID 38674929, 2024). "Our experimental results demonstrate that the PNPLA3 rs738409 GG variant LAMPS exhibits increased steatosis in NF, EMS, and LMS media compared to the wild-type CC LAMPS, consistent with the clinical characterization describing abnormal lipid homeostasis in these patients." (PMID 39324073, 2024). "Additionally, some studies have found that certain variants are associated with the risk of developing ALD, such as PNPLA3, which was found to modulate the evolution of steatosis, necroinflammation, fibrosis, and HCC in alcoholics." (PMID 36845083, 2023). "In addition, the association between PNPLA3 I148M polymorphism and steatosis severity was weaker in individuals with a poor vegetable diet." (PMID 37304843, 2023). "Here we use human fetal hepatocyte organoids to model the first stage of NAFLD, steatosis, representing three different triggers: free fatty acid loading, interindividual genetic variability (PNPLA3 I148M) and monogenic lipid disorders (APOB and MTTP mutations)." (PMID 36823355, 2023). "Carrying the PNPLA3 I148M variant attenuated organoid responses towards steatosis-reducing drugs." (PMID 36823355, 2023). "We found that dietary niacin showed a trend of reduction in patients carrying the PNPLA3 at-risk G allele and BMI ≥ 30 kg/m2 whereas by stratifying patients according to the presence of severe steatosis the lower levels of niacin in subjects with the PNPLA3 CG/GG mutation didn’t vary across BMI." (PMID 36937355, 2023). "A second mechanism that may underlie the anti-steatosis effect of BemA is the increase in PNPLA3 expression." (PMID 35884822, 2022). "The G variant in PNPLA3 was recorded in 53% of cases, thus demonstrating that PNPLA3 I148M accounts for more than half of the interethnic variability in predisposition to liver disease, especially steatosis, steatohepatitis, and fibrosis of varying origin (viral, alcohol, or metabolic)." (PMID 36110512, 2022). "Together, our data and recent reports indicate that PNPLA3 polymorphism might be a useful surrogate tool for monitoring the dynamic changes of steatosis, as well as a predictive biomarker for HCC after SVR." (PMID 35696400, 2022).
steatosis (continued). "For possible reasons, a single-nucleotide polymorphism, rs738409 (causing an isoleucine-to-methionine substitution at position 148, I148M) in the patatin-like phospholipase domain-containing protein 3 (PNPLA3) gene is strongly associated with steatosis in patients with NAFLD." (PMID 36558395, 2022). "Recent genome-wide association studies (GWAS) showed that the single-nucleotide polymorphism (SNP) of patatin-like phospholipase domain-containing protein 3 (PNPLA3) rs738409 was the most significant genetic risk factor for steatosis, fibrosis, and hepatocellular carcinoma in NAFLD." (PMID 35886046, 2022). "LOC100344884, the ortholog for Pnpla3, expresses lipase activity towards triglycerides in hepatocytes and retinyl esters in hepatic stellate cells and was strongly associated with hepatic cholesterol content, fibrosis and steatosis." (PMID 35456988, 2022). "Consistent with its well‐established harmful effect on NAFLD in adults, rs738409C>G in PNPLA3 was associated with a higher grade of steatosis (p = 2.8 × 10−4), lobular inflammation (p = 0.026), and fibrosis stage (p = 0.007) on multivariable ordinal regression adjusted for age and sex." (PMID 35411667, 2022). "However, progressive steatosis was observed in a proportion of patients, particularly among individuals with metabolic derangement and PNPLA3 variants." (PMID 35696400, 2022). "In addition, in patients with autoimmune hepatitis, the PNPLA3 I148M variant has been associated with the progression of liver disease despite steatosis being similar across all PNPLA3-rs738409 genotypes." (PMID 36454904, 2022). "Indeed, PNPLA3 rs738409 variant is identified from genome-wide association study as a genetic marker associated with steatosis susceptibility." (PMID 35696400, 2022). "First, absence of metabolic and serum lipid profiles and assessments of steatosis and steatohepatitis data considering lipid metabolism related effects of PNPLA3 and especially TM6SF2 variants analyzed is a limitation, which would have otherwise provided useful insights to the study in this regard." (PMID 36028802, 2022). "The key mechanism of PNPLA3-148M causing steatosis is very complicated." (PMID 34476007, 2021). "The PNPLA3 variant is associated with steatosis, fibrosis, and liver cancer." (PMID 34503201, 2021). "In this context, the aim of this study is to describe the prevalence of TM6SF2 and PNPLA3 polymorphisms in Brazilian patients with chronic hepatitis C naïve for antiviral therapy, and to evaluate their association with liver fibrosis, steatosis, and other components of the metabolic syndrome." (PMID 33622266, 2021). "Correlated with the PNPLA3 polymorphism, fibrosis regression was more frequently observed in 84.6% of GG genotype subjects and 79.3% of CC genotype subjects (p = 0.279), and steatosis regression was more frequently observed (82.8%) in CG genotype patients and 81% of CC genotype patients (p = 0.554)." (PMID 34833371, 2021). "Genotyping for PNPLA3 could become part of the screening for patients with steatosis, as it might predict the risk for nonalcoholic steatohepatitis (NASH), hepatocellular carcinoma and cardiovascular disease." (PMID 34833467, 2021). "However, the third donor had two wild-type alleles in the PNPLA3 gene and developed the same degree of steatosis as the PNPLA3 I148M variants." (PMID 34036256, 2021). "Since then, numerous GWAS reports have shown that PNPLA3 rs738409[G] (148M) variant is associated with hepatic triglyceride accumulation (steatosis), inflammation, fibrosis, cirrhosis, and even hepatocellular carcinoma regardless of etiologies including alcohol- or obesity-related and others." (PMID 31921875, 2019). "With regard to NAFLD, the PNPLA3 I148M polymorphism is a clear example of these possible interactions: individuals with the PNPLA3 I148M polymorphism are more prone to develop steatosis when the intake of carbohydrates, in particular simple sugars, is elevated." (PMID 28954437, 2017).
steatosis (continued). "However, biopsies from PNPLA3 variant carriers showed higher degree of steatosis (p = 0.022), DR (p = 0.044), IH (p = 0.027), and a higher number of αSMA+ portal/septal MFs (p = 0.040) and portal S100A9+ macrophages (p = 0.039) when compared with WT patients." (PMID 29150621, 2017). "The association between the PNPLA3 variant and steatosis or severity of histological liver disease has been widely observed in the majority of subsequent genome-wide association studies and several case-control studies, including those in Chinese, Korean, and Japanese populations." (PMID 27247565, 2016). "In this study, besides confirming the associations between PNPLA3 C>G SNP and steatosis/lobular inflammation, for the first time we also highlighted the potential impact of GCKR C→T SNP on liver fibrosis in an European cohort of histologically diagnosed NAFLD patients." (PMID 24498332, 2014). "Since PNPLA3 I148M interferes with hepatocellular lipid metabolism, we next evaluated whether the effect of PNPLA3 148M/M on FPR was influenced by steatosis severity and risk factors for derangement of hepatic lipid metabolism." (PMID 25171251, 2014). "Furthermore, it has been suggested that steatosis is dissociated from insulin resistance in the I148M variant of PNPLA3." (PMID 25411786, 2014). "Moreover, PNPLA3 148M allele carriers with HCV infection have been reported to have increased prevalence of steatosis, fibrosis, cirrhosis and hepatocellular carcinoma." (PMID 22978414, 2012). "With respect to genotype, importantly, the patatin-like phospholipase domain containing 3 (PNPLA3) I148M variant, which has a global prevalence of 30 to 50%, is known to impair hepatic lipid metabolism and mitochondrial function, contributing to the development of steatosis and liver injury." (PMID 39842721, 2025). "In addition, we observed genotype-specific differences in response to drug treatment as resmetirom demonstrated greater efficacy in the PNPLA3 wild-type CC LAMPS than that in the GG variant in the reduction of steatosis, stellate cell activation, and the secretion of marker COL1A1." (PMID 39324073, 2024). "There is mixed evidence on the effects of dietary carbohydrates on liver outcomes, but it was suggested that dietary patterns, including intake of sweetened beverages and vegetables, may interact with the PNPLA3 rs738409 variant to influence the severity of steatosis." (PMID 36830856, 2023). "Previously, several studies based on primarily Caucasian and some Asian datasets have suggested association of PNPLA3 risk variant with increased severity of hepatic fibrosis and cirrhosis and enhanced progression of liver fibrosis or cirrhosis or independent steatosis in CHC settings." (PMID 36028802, 2022). "Interestingly, when patients with MetS were separately considered (N = 32), biopsies from PNPLA3 variant carriers (N = 23) still showed significantly higher degree of steatosis (p < 0.05), DR (p < 0.05), and portal inflammation (p < 0.05) when compared with WT patients (N = 9)." (PMID 29150621, 2017). "Moreover, in NASH biopsies, PNPLA3 variant carriers showed higher degree of steatosis (p = 0.025), portal inflammation (p = 0.034), DR (p = 0.036), EpCAM+ hepatocytes (p = 0.029), and higher number of αSMA+ portal/septal MFs (p = 0.011) when compared with WT patients." (PMID 29150621, 2017). "Hispanic ethnicity and genetic polymorphisms in PNPLA3, TM6SF2, GCKR, MBOAT7, and HSD17B13 are associated with steatosis-related lipotoxicity and oxidative DNA damage, which can contribute to hepatocarcinogenesis." (PMID 40995256, 2025). "Notable single nucleotide polymorphisms (SNPs), including PNPLA3 rs738409, TM6SF2 rs58542926, MBOAT7 rs641738, and GCKR rs1260326, are consistently linked to steatosis, inflammation, and fibrosis in MASLD." (PMID 40943344, 2025).
steatosis (continued). "Experimental models using patient-derived liver spheroids have demonstrated heightened steatosis and fibrogenesis in PNPLA3 GG carriers, with differential responses to emerging therapies such as resmetirom, a thyroid hormone receptor-β agonist." (PMID 40981175, 2025). "Together these data suggest that PNPLA3 I148M targeting and accumulation on LDs is required for initiating steatosis and further support a model by which PNPLA3 I148M sequesters ABHD5 and prevents activation of PNPLA2." (PMID 39814233, 2025). "For instance, a recent Japanese study revealed that the HSD17B13 rs6834314 AG + GG genotypes were related to enhanced steatosis but displayed a reduced effect of PNPLA3 on advanced fibrosis." (PMID 40725464, 2025). "The PNPLA3 genotype also interacts with meat intake, carbohydrate intake, smoking, and sugar-sweetened beverage intake to exacerbate the deleterious effects on steatosis of these dietary patterns." (PMID 40166930, 2025). "Variants in PNPLA3, GCKR, MBOAT7, and TM6SF2 were variably associated with liver injury and steatosis markers, with cohort-specific effects." (PMID 40943344, 2025). "In univariate analysis, parameters associated with significant fibrosis were age, the presence of T2DM and HT, AST, platelet, steatosis grade, PNPLA3 rs738409, VCTE, and all serum fibrosis biomarkers." (PMID 40002828, 2025). "Silencing PNPLA3 using GalNAc-conjugated ASOs has demonstrated reductions in hepatic lipogenesis and steatosis in preclinical studies." (PMID 40002806, 2025). "In a study of 84 obese patients undergoing MBS, those with PNPLA3 rs738409 showed higher hepatic triglyceride content, MRI-detected steatosis, and lower serum glucose levels pre-surgery." (PMID 39125390, 2024). "As a result, decreasing SREBP-1 activity is likely to diminish PNPLA3 expression and ameliorate related steatosis." (PMID 38674929, 2024). "PNPLA3-LAMPS demonstrate overall excellent reproducibility for steatosis, fibrosis, and immune activation when disease state, genotype and patient cohort are segmented." (PMID 39324073, 2024). "Background/Objectives: This study evaluated the association between polymorphisms in the PNPLA3, TM6SF2, HSD17B13, and SIRT5 genes and the severity of fibrosis and steatosis in metabolic dysfunction-associated steatotic liver disease (MASLD)." (PMID 39596570, 2024). "We also observed greater resmetirom efficacy in the PNPLA3 wild-type CC LAMPS compared to the GG variant in multiple MASLD metrics, including steatosis, stellate cell activation, and the secretion of pro-fibrotic markers." (PMID 39324073, 2024). "The findings suggest that PNPLA3 genetic factors play a role in steatosis development in WD, emphasizing the need for further investigations into hepatic copper concentration and ATP7B mutations in this context." (PMID 38397999, 2024). "We performed drug screening and identified compounds effective at resolving steatosis across these different models, while highlighting that PNPLA3 I148M impairs drug response." (PMID 36823355, 2023). "Liver targeting of triantennal n-acetyl galactosamine-coupled ASO mediated Pnpla3 silencing reduced liver lipogenesis and steatosis in mice carrying a human I148M mutant." (PMID 37753315, 2023). "Clonal FatTracer; PNPLA3−/− lines displayed a substantially worsened steatosis level, reaching around 50%, which is near double the steatosis level of FatTracer." (PMID 36823355, 2023). "PNPLA3−/− organoids most extensively accumulated lipids (around 8% steatosis), followed by homozygous I148M organoids (around 5%) and heterozygous I148M organoids (around 2%)." (PMID 36823355, 2023). "One important factor seems to be that PNPLA3 148M is more resistant to ubiquitylation and accumulates on lipid droplets, which leads to steatosis." (PMID 36499681, 2022).
steatosis (continued). "The objective of this study was to determine the association between variants of PNPLA3, TM6SF2, and MBOAT7-TMC4 and the three histologic stages of NAFLD (steatosis, NASH, and fibrosis) in PLWHIV." (PMID 36110512, 2022). "At FUw72, patients carried PNPLA3 CG+GG tended to have higher frequency of steatosis compared to those with CC genotype, although the significance was not reached [17(44.7%) vs. 12(26.7%), P = 0.108]." (PMID 35696400, 2022). "The degree of steatosis was slightly higher in homozygous PNPLA3(I148M)-carriers, accompanied by a significant increase in LD-size." (PMID 36611868, 2022). "In subjects eligible for bariatric surgery, PNPLA3 and GCKR were associated with steatosis and fibrosis." (PMID 33804302, 2021). "Although the proposed mechanisms link the PNPLA3 protein with steatosis and, to a lesser extent, fibrogenesis, there is yet insufficient data on its role in HCC development." (PMID 34830997, 2021). "Since then, many GWAS and EWAS have identified a relationship between PNPLA3 and steatosis measured by other imaging methods, histologically defined steatosis, hepatocyte ballooning, lobular inflammation, fibrosis, and cirrhosis and cT1 defined NASH." (PMID 34950105, 2021). "Recent studies have indicated that I148M PNPLA3 influences steatosis and/or fibrosis development in patients with HCV." (PMID 34833371, 2021). "PNPLA3 has been identified in children and adults who are sensitive to NAFLD and was associated with the severity of steatosis, acinar inflammation, hepatocyte bloating, and fibrosis." (PMID 34833467, 2021). "The TM6SF2 variant rs58542926 known as p.E167K was associated with steatosis and fibrosis in NASH patients, independently of diabetes mellitus (DM), obesity or PNPLA3 variant." (PMID 34830997, 2021). "It is not a surprise, therefore, that these are variants in genes—like PNPLA3 and TM6SF2—where the minor alleles alter protein function and promote steatosis, associated with both qualitative and quantitative alterations in hepatic fat content." (PMID 33808740, 2021). "The patatin-like phospholipase domain-containing 3 (PNPLA3) has a genetic association with NALFD, and mice showed accumulation of inactive PNPLA3 in lipid droplets and increased steatosis in high-fat diet feeding." (PMID 34992540, 2021). "By stratifying patients according to the presence of the PNPLA3 p.I148M allele, the PCSK7 rs236918 polymorphism was associated with advanced steatosis." (PMID 34680476, 2021). "The influence of PNPLA3 (CC, CG, GG) genotype among these patients on the degree of post-treatment regression of steatosis and fibrosis was assessed." (PMID 34833371, 2021). "If the mechanistic basis for steatosis is similar in mice and humans then therapeutic interventions that lower PNPLA3-I148M protein levels are likely to be beneficial in ameliorating the condition in carriers with this variant." (PMID 31062641, 2019). "This strategy has been demonstrated to be effective in ameliorating fibrosis and steatosis in PNPLA3-I148M KI mice." (PMID 31062641, 2019). "Clinical studies on patients with NAFLD have demonstrated that statins have a positive impact by diminishing steatosis, NASH, and fibrosis, although the presence of the PNPLA3 genetic variant blunted these beneficial effects." (PMID 31497741, 2019). "Similar to the PNPLA3 I148M variant, the TM6SF2 E1267K variant not only increases the risk of steatosis, but has also been associated with increased risk of progressive liver disease and fibrosis." (PMID 30355853, 2018). "The genetic variation in PNPLA3 has been previously shown to play a role in the increase of FA accumulation in liver leading to steatosis." (PMID 30279702, 2018). "The highest area under the ROC curve (AUC) for steatosis of PNPLA3 rs738409 genotype, 8 proteins, or 19 phenotypic variables was 0.913, whereas the final classifier that included variables from all three domains had an AUC of 0.935." (PMID 28266614, 2017).